RN7SL300P (RNA, 7SL, cytoplasmic 300, pseudogene)
Gene: Miscellaneous RNA gene on chromosome 3 (153,199,700 to 153,200,017, reverse strand). Ensembl gene ENSG00000265813.
Homologues: Orthologues: chimpanzee Metazoa_SRP (99% identical), macaque Metazoa_SRP (85% identical). Paralogues in human: RN7SL2 (82% identical), RN7SL1 (81% identical), RN7SL3 (79% identical), RN7SL326P (78% identical), RN7SL45P (78% identical), RN7SL444P (77% identical), RN7SL451P (77% identical), RN7SL304P (77% identical), RN7SL492P (77% identical), RN7SL769P (77% identical), RN7SL543P (77% identical), RN7SL88P (77% identical), and 702 more.